DDR1 (discoidin domain receptor tyrosine kinase 1)
Diseases named in the same sentence as DDR1 in open-access papers (continued):
Sharing a sentence is not in itself a finding about the gene and the disease.
tumor (continued). "Beyond its intracellular enzymatic role in tumor proliferation, the extracellular non-enzymatic domain of DDR1 has been implicated in promoting immunosuppressive effects within the tumor microenvironment." (PMID 40713963, 2025). "COL4A6 may promote tumor aggressiveness and chemoresistance via the E2F/DDR1 axis, and COL4A6 expression can predict clinical outcomes in patients with OC." (PMID 40603853, 2025). "DDR1 is known to be involved in the maintenance of proliferation, migration, invasion, stromal remodelling, apoptosis resistance, immune escape, and resistance to therapy in tumour cells." (PMID 40105492, 2025). "DDR1 expression was also significantly greater in tumor samples from patients over 65 years of age (over 65 years: 7.14 ± 0.917 vs. under 65 years: 6.94 ± 1.03, P < 0.05) and females (female: 6.89 ± 0.95 vs. Male: 7.18 ± 0.963, P < 0.05) compared to the corresponding reference groups." (PMID 41394854, 2025). "This suggests that targeting DDR1 can disrupt key signaling pathways involved in tumor progression." (PMID 40713963, 2025). "However, DDR1 protein was detected in tumour cells in 38/90 cases, confirmed by costaining for CD20 and DDR1." (PMID 40401507, 2025). "Similarly, the expression of DDR1 is significantly negatively correlated with the tumor stromal score in 22 cancer types, including IBC (BRCA in TCGA), LUAD, STAD, and PAAD." (PMID 40869052, 2025). "Although TMB and MSI are typically predictive of favorable immunotherapy outcomes due to increased neoantigen load and immune activation, our findings suggest that DDR1 may counteract these benefits by fostering an immune-excluded tumor microenvironment." (PMID 40869052, 2025). "Notably, DDR1-high PDAC tumors skew toward M2-polarized macrophages, a phenotype typically associated with immunosuppression and tumor progression." (PMID 40869052, 2025). "Based on the role of DDR1 in HNSCC in tumor progression and immune escape, we believed that DDR1 could be a promising target for the combined application of CIR, thereby improving the therapeutic effect of HNSCC." (PMID 40993737, 2025). "However, the activation of DDR1 signaling is expected to occur in both tumor and cell line samples as either the increases of collagen ligands or the DDR1 receptor should activate DDR1 signaling." (PMID 40025071, 2025). "Furthermore, resistance to DDR1 inhibitors can develop as tumor cells reactivate DDR1-related signaling pathways." (PMID 40713963, 2025). "However, current small-molecule inhibitors and antibodies primarily target DDR1's kinase activity or extracellular domain, failing to fully disrupt its involvement in tumor progression." (PMID 40713963, 2025). "Moreover, DDR1-selective small-molecule inhibitors displayed potent GC tumor inhibitory effects, particularly in DDR1-overexpressing cells." (PMID 40456688, 2025). "Surprisingly, the knockdown of DDR1 further augmented the tumor cell immunogenicity induced by CIR, accompanied by increased intratumoral CD8 + T cell infiltration, Granzyme B and IFN-γ production, indicating an enhancement in the killing capacity of immune cells." (PMID 40993737, 2025). "When DDR1 was removed, increased T cell infiltration and reduced tumor size were observed." (PMID 39513932, 2024). "Furthermore, the western blot analyses showed that the RhoA signaling was also upregulated in AGS‐DDR1 tumor xenografts, and DDR1 overexpression promoted EMT process in tumor xenografts." (PMID 39024501, 2024). "However, there are still confounding findings on which type of collagens is active on DDR1, even in the same tumor type." (PMID 38907027, 2024). "In PDAC, two different studies have shown opposite conclusions, demonstrating that stromal-cleaved collagen triggers DDR1 via NF-κΒ signaling, thereby enhancing mitochondrial dynamics and tumor growth, while the homotrimeric (i.e., intact) collagen activates DDR1/FAK/ERK in a cell-autonomous manner." (PMID 38907027, 2024).
tumor (continued). "Currently, the mechanism underlying DDR1's function in tumor angiogenesis has not been reported yet." (PMID 39024501, 2024). "Given prior speculation that DDR1‐dependent collagen barriers impede immune cell infiltration, we examined the T‐cell proportions in tumor." (PMID 38953306, 2024). "Pharmacological inhibition of DDR1 retarded tumor progression in PDX and organoid models." (PMID 39024501, 2024). "Moreover, DDR1 pathway activation mediated by type I collagen inhibits tumor cell growth, through the pro-apoptotic factor BCL-2 interacting killer (BIK), a member of the BCL2 family." (PMID 39769286, 2024). "The abundant collagen within the ECM significantly influences tumor progression and matrix‐mediated drug resistance (MMDR) by binding to discoidin domain receptor 1 (DDR1), but the specific mechanisms by which tumor cells modulate ECM via DDR1 and ultimately regulate TME remain poorly understand." (PMID 38953306, 2024). "However, the functional role of DDR1 activity in mediating tumor resistance in CRC has been poorly documented." (PMID 38953306, 2024). "In addition, rhCOLIII treatment increased DDR1 protein expression, inhibiting autophagy of tumor cells." (PMID 39769286, 2024). "We hypothesized a peculiar role of tumor cell-derived collagen induced by stromal lactate, specifically acting as a signaling molecule via DDR1." (PMID 38907027, 2024). "In addition, 8 paired nontumor and tumor tissues from GC patients in the First Affiliated Hospital of Sun Yat‐sen University (FAHS) were analyzed, and we found that DDR1 expression was also higher in the tumor tissues in this cohort." (PMID 39024501, 2024). "DDR1‐mediated ECM remodeling hinders deep tumor drug delivery." (PMID 38953306, 2024). "In addition, MMP-cleaved type I collagen remodeling activates the DDR1/NF-κB/p62/NRF2 signaling pathway to promote tumor metastasis regulates tumor growth and metabolism, and promotes PC growth." (PMID 39872846, 2024). "Silencing of HIF1A significantly attenuated DDR1‐increased tumor growth in nude mice." (PMID 39024501, 2024). "Samples were grouped according to DDR1 expression (low, <50% vs. high, ≥50% or low, <25% vs. high, ≥75%) and were compared to FoxP3, a nuclear transcription factor present in Tregs that represents the main tumor-promoting CD4+ T-cell population." (PMID 38136314, 2023). "Adding to this, it has been proved that both mRNA and protein levels of DDR1 negatively correlate with genes that define anti-tumour immunity, a gene expression signature for intratumoral T cell accumulation, CD8+ T cell signature scores, and the cytolytic effector pathway." (PMID 37284199, 2023). "To verify DDR1 expression and its relationship with tumor functional status at the single-cell level in different cancers, using the CancerSEA database, we found that DDR1 expression was correlated with angiogenesis, DNA damage, hypoxia, stemness, metastasis, and DNA repair in most cancers." (PMID 37031216, 2023). "Indeed, this is not a surprising issue due to the previously reported modulating effect of DDR1 on TGFBI which often acts as a tumor promoter." (PMID 37271822, 2023). "Therefore, comprehensive DDR1 analyses based on prognosis, tumor microenvironment, immune efficacy, and therapeutic efficacy in all cancer types are needed." (PMID 37031216, 2023). "Furthermore, the extracellular matrix (ECM) of the tumor microenvironment was enhanced by the extracellular domain of DDR1, which inhibited tumor T-cell infiltration and promoted tumor growth in a triple-negative breast cancer mouse model." (PMID 37031216, 2023). "Since non-tumor-related factors may lead to death during follow-up, we analyzed the relationship between DDR1 expression and DSS in 33 cancer types." (PMID 37031216, 2023). "Collagen XV-mediated DDR1 suppression inhibits tumor invasion in PDAC." (PMID 36906534, 2023). "Conflicting tumor-suppressing and tumor-promoting roles for DDR1 have been documented." (PMID 36765910, 2023).
tumor (continued). "Silencing DDR1 significantly reduced tumour migratory ability and metastatic growth in the liver." (PMID 37007062, 2023). "In addition, DDR1 expression was also significantly correlated with immune cell infiltration, tumor microenvironment, immune-related genes, and drug resistance in various cancers." (PMID 37031216, 2023). "Previous studies suggest that activated ARF6 plays important role in tumor progression, we wondered whether DDR1 could regulate ARF6 activation." (PMID 35140331, 2022). "In preclinical models, Col I remodelling modulated tumour growth and metabolism through a DDR1–NF-κB–p62–NRF2 cascade that is activated by cCol I and inhibited by iCol I. The activation of DDR1 by collagens and downstream activation of NF-κB have been described before." (PMID 36198801, 2022). "DDR1 is upregulated in many epithelial cancers and plays important roles during tumor development." (PMID 35936735, 2022). "In addition to MCP1, DDR1 activation in pancreatic cancer cells initiates PKCθ/SYK/NF-κB signaling cascade which increases CXCL5 production and results in the recruitment of tumor associated neutrophils and formation of neutrophils extracellular traps." (PMID 36249782, 2022). "Considering the tumor grades, DDR1 was more expressed in tumor grades 1–3 than in normal control." (PMID 35935941, 2022). "Together, our data demonstrate that DDR1 exerts a tumor-promoting role in HCC progression, and could be a potential therapeutic target for HCC metastasis." (PMID 35140331, 2022). "With the adjustment based on purity, the correlation analysis in STAD revealed that DDR1 was closely linked to most of immune markers in various TIICs, such as CD3E of general T cells, CD86 of monocytes, CCL2 of tumor-associated macrophages (TAMs), and CCR7 of neutrophils." (PMID 35935941, 2022). "DDR1 immunostaining was diffuse (>50% of positive tumor cells) in all cases." (PMID 35205677, 2022). "Therefore, the molecular mechanisms and signaling pathways of DDR1 affecting immune infiltration and escape, tumor invasion, and metastasis also remain to be further studied." (PMID 35935941, 2022). "Moreover, ARF6 is required for DDR1-mediated tumor cell migration and invasion, suggesting that ARF6 and DDR1 function together to regulate the development of HCC." (PMID 35140331, 2022). "Overall, this study further highlights the important role of DDR1 in tumor immune evasion." (PMID 35936735, 2022). "The data showed that the tumor cell invasion capacity is closely correlated to DDR1 expression." (PMID 35205677, 2022). "In a mouse model of TNBC, high expression of DDR1 at the tumor border correlated with low intratumoral T cells, while an anti-DDR1 mAb could intensify the immune infiltration." (PMID 36230808, 2022). "Still, their DDR1 antibody gave a similar anti-tumor effect, suggesting that DDR1 may have a tumor-promoting function at later stages of tumor development." (PMID 35936735, 2022). "Similarly, in DDR1-knocked down HLF and HLE cells, overexpressed ARF6Q67L greatly rescued the inhibitory effects of tumor cells migration and invasion when DDR1 silenced." (PMID 35140331, 2022). "Through analyzing the clinicopathological features of patients with HCC, we found that high expression of DDR1 was significantly correlated with poor tumor differentiation (P = 0.019), incomplete tumor encapsulation (P = 0.029), advanced tumor TNM stage (P = 0.012), and tumor recurrence (P = 0.001)." (PMID 35140331, 2022). "Similarly, in a KRAS-mutant lung adenocarcinoma mouse model, inhibition of DDR1 attenuated tumor aggression." (PMID 33888679, 2021). "Moreover, the miR-199b-5p expression was remarkably reduced in the xenograft tumours, along with the downregulated expression of E-cadherin and the upregulated expression of DDR1, vimentin and fibronectin." (PMID 33239676, 2021). "Interestingly, the function of DDR1 in tumor growth and metastasis displayed an epithelial-specific expression has been previously recognized." (PMID 33840167, 2021).
tumor (continued). "This H-Ras/ZEB1/DDR1 network interacts to promote tumor progression." (PMID 34805157, 2021). "For corroborating these findings, we performed IHC to evaluate the expression levels of DDR1 protein in the tumour xenografts and metastatic tumours tissues derived from the mice injected with miR-199b-5p, anti-iR-199b-5p and NC-transfected LNCaP and PC-3 cells." (PMID 33239676, 2021). "The tumor cells-microenvironment interaction loop predicted that blockade of either TGF-β1 signaling in microenvironmental HSCs or DDR1 signaling in UM cells might inhibit in vivo metastatic colonization." (PMID 33976105, 2021). "We demonstrate that collagen-induced DDR1 activation in cancer cells is a major stimulus for CXCL5 production, resulting in the recruitment of tumor-associated neutrophils (TANs), the formation of neutrophil extracellular traps (NETs), and subsequent cancer cell invasion and metastasis." (PMID 34237033, 2021). "Knocking down DDR1 reduced the level of CXCL5 in the primary tumor and plasma." (PMID 34237033, 2021). "Moreover, an in vivo study showed that the knockdown of DDR1 suppressed tumor growth and multiorgan metastasis in breast cancer mouse models." (PMID 33888679, 2021). "Interestingly, the phagocytosis of apoptotic cells is mediated by MERTK in macrophages and DDR1 induces apoptosis through the upregulation of pro-apoptotic tumor suppressors." (PMID 34830178, 2021). "Furthermore, DDR1 was upregulated in PCa, and significantly correlated with high Gleason score, advanced pathological stage, tumour metastasis and shorter overall survival." (PMID 33239676, 2021). "Overall, these evidences support the hypothesis that tumour-suppressive effects of miR-199b-5p are ascribable to its ability to directly repress DDR1." (PMID 33239676, 2021). "In non-small-cell lung carcinoma (NSCLC), DDR1 induces tumor cell proliferation in vivo." (PMID 33917302, 2021). "Also, DDR1 signaling in tumors aids in tumor progression, metastasis, and resistance to chemotherapy." (PMID 34837026, 2021). "As DDR1 tumor-promoting function in CRC requires its kinase activity, small DDR1 kinase inhibitors might be of therapeutic value." (PMID 32117772, 2020). "Because DDR1 is a collagen receptor and collagen accumulation in the oral cavity is an early event in OSCC pathogenesis, we asked whether DDR1 overexpression is concurrent with collagen accumulation in the 40 tumor tissues of NCKU-OrCA-40TN." (PMID 32244515, 2020). "Alternatively, it may also derive from the reduction in the density of activated HSCs inside the tumor in DDR1-silenced livers." (PMID 33110221, 2020). "Finally, a role for DDR1 signaling in cell proliferation has been proposed in several tumor cell lines." (PMID 32090682, 2020). "DDR1 expressed by gastric cancer cells supports invasion and tumour metastasis." (PMID 33037194, 2020). "Thus, we carried out chemotaxis assay and tested the ability of siDDR1 cells to invade collagen I-coated wells compared to tumor cells with full expression of DDR1." (PMID 32090682, 2020). "Finally, DDR1 inhibition displays anti-tumor activity in mice that have already developed DDR1-dependent metastatic nodules, revealing an additional important DDR1 role in metastatic growth." (PMID 32117772, 2020). "Silencing of DDR1 before tumor inoculation reduced hepatic C26 metastasis in mice." (PMID 33110221, 2020). "Even more, DDR1-IN-1 lowered DDR1 phosphorylation in tumor-activated HSCs by ~ 40%." (PMID 33110221, 2020). "Taken together, these results suggest that collagen deposition in the affected tissues followed by DDR1 overexpression could be central to OSCC tumor growth and angiolymphatic invasion." (PMID 32244515, 2020). "DDR1 mRNA levels drastically variate between tumor cell lines." (PMID 32090682, 2020). "Thus, the invasion of the collagenous ECM requires both MMPs and DDR1 synthesis by these tumor cells." (PMID 32090682, 2020).
tumor (continued). "Anlotinib suppresses tumor cell proliferation via inhibition of platelet-derived growth factor receptors α/β (PDGFR α/β), c-Kit, ret, as well as Aurora-B, c-FMS, and discoidin domain receptor 1 (DDR1), which are a group of newly identified kinase targets involved in tumor progression." (PMID 32266457, 2020). "Next, we investigated whether the composition of the tumor stroma is affected by the level of hepatic DDR1." (PMID 33110221, 2020). "Next, we studied DDR1 mRNA expression in the three tumor cell lines." (PMID 32090682, 2020). "Silencing of hepatic DDR1 resulted in a ~ 28% reduction in the number of small avascular micrometastases characterized by their lack of infiltrating stroma, which may indicate a role for hepatic DDR1 in tumor cell implantation." (PMID 33110221, 2020). "Since then, many evidences of an important DDR1 tumor-promoting role in metastasis development have been reported, although this activity may depend on the tumor type and the collagen microenvironment nature." (PMID 32117772, 2020). "Finally, we confirm the presence of DDR1 in the lysates of tumor cells cultured in the presence of exogenous collagen I." (PMID 32090682, 2020). "However, the anti‐tumor efficacy of these DDR1 inhibitors which depend on DDR1 signaling for cancer cells survival is limited to suppress tumor growth and not sufficient to induce complete tumor regression in vivo." (PMID 31116512, 2019). "Whether anti‐DDR1 ADC can coordinate with checkpoint immunotherapy for tumor deserves further research." (PMID 31116512, 2019). "There is a significant difference in DDR1 expression between tumor tissues and normal tissues." (PMID 31116512, 2019). "This low level of DDR1 is yet sufficient to promote tumor invasion in a kinase-independent manner." (PMID 31130862, 2019). "Clinically approved multi‐kinase inhibitors, such as nilotinib, inhibit DDR1‐mediated tumor growth in xenograft models, suggesting DDR1 might be a potential target for cancer treatments." (PMID 31116512, 2019). "Interestingly, studies have shown that a low DDR1 expression is correlated with poor relapse-free survival, confirming its controversial role in tumor progression." (PMID 31130862, 2019). "One reason for the difference is that DDR1 is collagen dependent and there may be differences in the 3D structure of the tumor and the cell lines growing on the plate." (PMID 30615629, 2019). "First, DDR1 could promote local invasion of primary tumour cells and the invasive properties of disseminated CRC cells, which is essential for metastasis formation." (PMID 29438985, 2018). "Nevertheless, we could detect DDR1 activity in a small group of samples from patients with mCRC, composed of matched healthy tissue, primary tumour and metastatic lesions, which were quickly frozen after resection." (PMID 29438985, 2018). "Our proteomic analyses support a model where sustained DDR1 activation upon collagen deposition at the tumour front or at the metastatic niche maintains a high level of β‐catenin transcriptional activity necessary for cancer stem cells dissemination and survival." (PMID 29438985, 2018). "We observed moderate DDR1 activation in matched primary tumour and healthy tissue samples." (PMID 29438985, 2018). "We then used this mutant to assess DDR1 role in nilotinib anti‐tumour activity in CRC." (PMID 29438985, 2018). "In support of this hypothesis, in metastatic tumours, DDR1 could contribute to increase the β‐catenin activity necessary for CRC metastasis growth." (PMID 29438985, 2018). "DDR1 may also promote cell proliferation, motility and invasion, depending on the tumour type and the nature of the microenvironment." (PMID 29438985, 2018). "Furthermore, our findings identify DDR1 as a target of C1q, and suggest that the interaction between the two promotes tumor aggressiveness." (PMID 29559654, 2018).